AARS2 (alanyl-tRNA synthetase 2, mitochondrial)
Description:
Catalyzes the attachment of alanine to tRNA(Ala) in a two-step reaction: alanine is first activated by ATP to form Ala-AMP and then transferred to the acceptor end of tRNA(Ala). Also edits incorrectly charged tRNA(Ala) via its editing domain. In presence of high levels of lactate, also acts as a protein lactyltransferase that mediates lactylation of lysine residues in target proteins, such as CGAS. Acts as an inhibitor of cGAS/STING signaling by catalyzing lactylation of CGAS, preventing the formation of liquid-like droplets in which CGAS is activated.
Synonyms: AARSL; KIAA1270; bA444E17.1; COXPD8; LKENP; MT-ALARS; MTALARS
Tractability: PROTAC: ubiquitination databases record sites on it; its protein half-life has been measured.
Gene: Protein-coding gene on chromosome 6 (44,298,726 to 44,313,347, reverse strand). Ensembl gene ENSG00000124608.
Subcellular location: Mitochondrion
Subcellular location (Human Protein Atlas): Mitochondria
Pathways (Reactome):
Metabolism of proteins: Mitochondrial tRNA aminoacylation
Gene Ontology:
Molecular function: alanine-tRNA ligase activity; peptide lactyltransferase (ATP-dependent) activity; protein binding; aminoacyl-tRNA deacylase activity; aminoacyl-tRNA ligase activity; ATP binding; nucleic acid binding; nucleotide binding; zinc ion binding
Biological process: mitochondrial alanyl-tRNA aminoacylation; negative regulation of cGAS/STING signaling pathway; alanyl-tRNA aminoacylation; aminoacyl-tRNA metabolism involved in translational fidelity; tRNA aminoacylation
Cellular component: mitochondrion; cytoplasm
Genetic constraint (gnomAD): Loss-of-function variants: 78 observed, 125.15 expected, observed/expected ratio (o/e) 0.62, 90% interval 0.52 to 0.75. The upper end of that interval is the gene's LOEUF score, 0.75, which puts it in group 3 of 6, group 1 being the genes least tolerant of losing a copy. Missense variants: 1,157 observed, 1,347.9 expected, observed/expected ratio (o/e) 0.86, 90% interval 0.82 to 0.9. Synonymous variants: 502 observed, 551.2 expected, observed/expected ratio (o/e) 0.91, 90% interval 0.85 to 0.98.
Gene-disease validity (ClinGen):
ClinGen rates the evidence that AARS2 causes each of these diseases.
mitochondrial disease (autosomal recessive): Definitive.
Homologues: Orthologues: chimpanzee AARS2 (99% identical), macaque AARS2 (96% identical), dog AARS2 (87% identical), pig AARS2 (85% identical), rabbit AARS2 (84% identical), guinea pig AARS2 (83% identical), mouse Aars2 (83% identical), rat Aars2 (80% identical), tropical clawed frog aars2 (61% identical), zebrafish aars2 (54% identical), Drosophila melanogaster AlaRS-m (34% identical). Paralogues in human: AARS1 (45% identical), AARSD1 (9% identical).
Diseases named in the same sentence as AARS2 in open-access papers:
AARS2 is named in the same sentence as 77 diseases in open-access papers, as found by Europe PMC text mining. Sharing a sentence is not in itself a finding about the gene and the disease. The quoted sentences say what the papers report.
Leukoencephalopathy (23 papers, 2014 to 2025). This term describes abnormality of the white matter of the cerebrum resulting from damage to the myelin sheaths of nerve cells. "For example, point mutations affecting the editing domain of AARS2 were linked to infantile onset cardiomyopathy, whereas mutations targeting its aminoacylation domain have been shown to cause leukoencephalopathy and ovarian failure in women." (PMID 37975900, 2024). "Several adult-onset cases of leukoencephalopathy and ovarian failure associated with AARS2 variants have been reported." (PMID 37456626, 2023). "The AARS2 is frequently reported that its mutation has significant correlations with leukoencephalopathy." (PMID 37990642, 2023). "Mutations in AARS2 have been confirmed as a key factor underlying cardiomyopathies and leukoencephalopathies." (PMID 37990642, 2023). "The mitochondrial alanyl-transfer (t)RNA synthetase 2 (AARS2) has been linked to leukoencephalopathy." (PMID 36107978, 2022). "Our findings further extend the mutational spectrum of AARS2-related leukoencephalopathy and highlight the importance of the whole-exome sequencing in precisely diagnosing adult-onset leukoencephalopathies." (PMID 35676634, 2022). "All of these findings strongly suggest that AARS2‐related leukoencephalopathy is a new variant of mitochondrial encephalomyopathy." (PMID 30706699, 2019). "We described the ragged red fiber (RRF) for the first time, suggesting that AARS2‐related leukoencephalopathy be a new variant of mitochondrial encephalomyopathy." (PMID 30706699, 2019). "We reported an adult‐onset male leukoencephalopathy patient related to novel AARS2 gene mutations and reviewed all previous cases regarding the clinical and genetic features of AARS2 leukoencephalopathy." (PMID 30706699, 2019). "Leukoencephalopathy due to AARS2 mutations is a syndrome with progressive cerebral white matter degeneration." (PMID 30706699, 2019). "Few examples of different phenotypes caused by mutations in the same aaRS gene have been reported (e.g. AARS2 associated with either cardiomyopathy or leukoencephalopathy and ovarian failure)." (PMID 29615062, 2018). "Remarkably, a recent study reported AARS2 mutations in patients who developed leukoencephalopathy and ovarian failure, with onset from childhood to adulthood, and no signs of a cardiomyopathy." (PMID 25705216, 2015). "AARS2 mutations can be also associated with a different clinical presentation, characterized by cerebellar ataxia and psychotic features with leukoencephalopathy." (PMID 24639874, 2014). "The patient carrying compound heterozygous AARS2 mutations (c.1709delG, p.G570Afs*21; c.1188G>A; splicing variant resulting in exclusion of exon 8) presented with rapidly progressing leukoencephalopathy leading to cognitive decline, upper limb tremor and hyperphagia." (PMID 37975900, 2024). "Additional cases of leukoencephalopathy linked to AARS2 mutations have been reported." (PMID 35683020, 2022). "To date, AARS2 mutations have been reported among patients with infantile mitochondrial hypertrophic cardiomyopathy with early fatal outcomes, and patients with late‐onset leukoencephalopathy." (PMID 30706699, 2019). "Here, for the first time we reported a typical RRF identified by muscle biopsy in a patient with AARS2‐related leukoencephalopathy, which suggests that AARS2‐related leukoencephalopathy might be a new variant of mitochondrial encephalomyopathy." (PMID 30706699, 2019). "However, mutations in the AARS2 gene for mitochondrial alanyl-tRNA synthetase (mtAlaRS) have been reported both in patients with infantile-onset cardiomyopathy and in patients with childhood to adulthood-onset leukoencephalopathy." (PMID 25705216, 2015). "Extrapyramidal symptoms are less frequent but, if present, can serve as useful diagnostic clues, such as parkinsonism in CSF1R-related leukoencephalopathy, chorea in Gordon Holmes syndrome, and dystonia in AARS2-related leukoencephalopathy." (PMID 37564735, 2023).
Leukoencephalopathy (continued). "Recessive mutations in alanyl-transfer (t)RNA synthase 2 (AARS2) cause leukoencephalopathy, progressive with ovarian failure (ALSP-AARS2: LKENP, OMIM # 615889)." (PMID 35683020, 2022). "Recessive mutations in alanyl-transfer (t)RNA synthase 2 (AARS2) cause leukoencephalopathy, progressive with ovarian failure (ALSP-AARS2 or LKENP, OMIM # 615889)." (PMID 35683020, 2022). "Both CSF1R- and AARS2-related leukoencephalopathy share several neurological symptoms and can present with similar white matter involvement, predominantly in the frontoparietal and periventricular regions." (PMID 35185751, 2021). "Further analyses of brain images and modern neuropathology are necessary to definitively characterize AARS2-related leukoencephalopathy." (PMID 35185751, 2021). "In conclusion, we report an AARS2‐related leukoencephalopathy case with typical RRF for the first time." (PMID 30706699, 2019). "It is noteworthy that this is the first reported case of AARS2‐related leukoencephalopathy with a typical RRF identified by muscle biopsy." (PMID 30706699, 2019). "Mutations in the mitochondrial alanyl‐transfer (t)RNA synthetase 2 (AARS2,OMIM:612035) have been linked to leukoencephalopathy recently." (PMID 30706699, 2019). "AARS2 leukoencephalopathy is attributed to a defect in mitochondrial alanyl-tRNA synthetase, only compound heterozygous mutations have been reported." (PMID 31839000, 2019). "Similarly, both CSF1R- and AARS2-related leukoencephalopathy share several neurological symptoms and can present with similar white matter involvement, predominantly in the frontoparietal and periventricular regions." (PMID 40443872, 2025). "The hallmark of EARS2 mutations is leukoencephalopathy with thalamus and brainstem involvement and high lactate (LTBL), and similar leukoencephalopathy with high lactate was also observed in patients with AARS2 mutations." (PMID 37975900, 2024). "All female patients with AARS2 mutation presented with ovarioleukodystrophy and ovarian failure, a feature not seen in other leukoencephalopathies." (PMID 30706699, 2019). "The characteristic MRI abnormalities and clinical symptoms described here may help to distinguish AARS2‐related leukoencephalopathy from other adult‐onset leukoencephalopathies." (PMID 30706699, 2019). "DARS, RARS, KARS, and AARS2 pathogenic variants caused ataxia with or without leukoencephalopathy." (PMID 38869703, 2024). "Due to the broader application of next-generation sequencing in clinical practice, we have been able to recognize the expanding phenotypic spectrum of AARS2 mutations, including a benign phenotype without leukoencephalopathy and lethal primary pulmonary hypoplasia." (PMID 35676634, 2022). "In AARS2 iNPCs, we detected downregulation of genes involved in axon guidance, TGF-β and MAPK signalling, suggesting an impairment of early neuronal development and potentially affecting maturation of oligodendrocytes, which are in line with early-onset leukoencephalopathy seen in patients." (PMID 37975900, 2024). "Therefore, ALSP is further divided into CSF1R- related leukoencephalopathy, AARS2- related leukoencephalopathy, and CSF1R/AARS2-negative ALSP." (PMID 34955818, 2021). "The five main classifications of leukoencephalopathies are CSF1R-related leukoencephalopathy, AARS2-related leukoencephalopathy, AARS1-related leukoencephalopathy, HDLS-S-related leukoencephalopathy and CSF1R/AARS1/AARS2-negative ALSP." (PMID 35185751, 2021).
leukodystrophy (14 papers, 2015 to 2025). Leukodystrophies are a group of rare, progressive, metabolic, genetic diseases that affect the brain, spinal cord and often the peripheral nerves. "New cases of leukodystrophy linked to AARS2 mutations have been reported in males and females with variable clinical course; some are accompanied by peripheral neuropathy." (PMID 35683020, 2022). "At present, a total of 15 sporadic AARS2 mutation-related leukodystrophy patients (including eight females and seven males) have been reported around the world." (PMID 31920941, 2019). "We also reviewed phenotypic spectra of AARS2 mutation‐associated leukodystrophies from a total of 16 reported cases." (PMID 31106991, 2019). "Recently, other studies reported patients with leukodystrophy as well as optic atrophy, retinopathy, and multiple peripheral demyelinating neuropathies, all of which were considered due to AARS2 missense mutations." (PMID 31920941, 2019). "In short, this study of five patients from four families showed that the AARS2 mutation causing leukodystrophy with ovarian failure is considered an autosomal recessive inherited disease, supplementing previous reports of scattered cases of deficiencies." (PMID 31920941, 2019). "Clinical manifestations of the 16 leukodystrophy patients carrying AARS2 mutations include cognitive decline, psychiatric symptoms, pyramidal symptoms, extrapyramidal signs, cerebellar symptoms, dystonia, and epilepsy." (PMID 31106991, 2019). "Structural analysis of cardiomyopathy and leukodystrophy mutations in AARS2 and assessment of their impact on the synthetase function based on modeled protein structure." (PMID 25705216, 2015). "The new AARS2 mutations reported in patients with leukodystrophy seemed, at first glance, to be scattered along the entire AARS2 gene, with some located in the aminoacylation domain and some in the editing domain." (PMID 25705216, 2015). "We show that the cardiomyopathy phenotype results from a single allele, causing an amino acid change R592W in the editing domain of AARS2, whereas the leukodystrophy mutations are located in other domains of the synthetase." (PMID 25705216, 2015). "We suggest that the two distinct phenotypes caused by AARS2 mutations are simply caused by differential effects on aminoacylation, with cardiomyopathy resulting from highly severe reduction in aminoacylation activity, and leukodystrophy resulting from only partial reduction in activity." (PMID 25705216, 2015). "It is intriguing why these two seemingly unrelated genes, CSF1R and AARS2, give rise to the same leukodystrophy." (PMID 34867307, 2021). "Future investigations on potential functional correlations between CSF1R and AARS2 may shed light on whether and how CSF1R and AARS2 mutations lead to leukodystrophy through common molecular mechanisms." (PMID 34867307, 2021). "LysRS are involved in myelin formation and defects in other ARSes (e.g., AARS2, DARS2, EARS2, and LARS2) have been found to be responsible for leukodystrophy." (PMID 33942428, 2021).
cardiomyopathy (12 papers, 2014 to 2025). A disease of the heart muscle or myocardium proper. "Taken together, these results suggested that activating PKM2 by TEPP-46 effectively alleviates cardiomyopathy in Aars2 deficient mice." (PMID 40371904, 2025). "Previous studies have shown that AARS2 mutations lead to abnormal cardiomyocyte function, eventually to cardiomyopathy in human patients." (PMID 40371904, 2025). "AARS2 c.1774 C>T (p.R592W) is a common missense founder mutation, found in nearly all AARS2-associated clinically fatal early onset cardiomyopathies, except our two recently identified patients with cardiomyopathy with AARS2 c.1738C>T (p.R580W) mutations." (PMID 30952159, 2019). "Several mutations in the AARS2 gene have been identified in patients with clinically fatal early onset cardiomyopathies." (PMID 30952159, 2019). "It is known that AARS2 deficiency causes human cardiomyopathy, but the underlying mechanisms remain unclear." (PMID 40371904, 2025). "However, the precise mechanisms by which AARS2 deficiency contributes to the development of cardiomyopathy in patients are not fully understood, and the potential of AARS2 as a therapeutic target for heart-related diseases remains to be explored." (PMID 40371904, 2025). "Childhood cardiomyopathies is typically caused by specific gene mutations, and the alteration of AARS2 might a crucial genetic basis." (PMID 37990642, 2023). "Indeed, in the AARS2 gene, R592W is a founder mutation, which is found in nearly all patients with AARS2-related cardiomyopathy, either homozygous or heterozygous with other mutations." (PMID 30952159, 2019). "We have previously hypothesized that in our cardiomyopathy patients, the AARS2 mutation resulting in R592W change, which is located in the editing domain of the synthetase, might interfere with tRNA binding, thus preventing editing, and resulting in mistranslation." (PMID 25705216, 2015). "For AARS2 mutations, the tissue-specific manifestation of the cardiomyopathy could be explained by variable amino acid concentrations in different tissues; in fact, increased levels of alanine have been found in affected tissue (heart and muscle), but not in the unaffected liver." (PMID 24639874, 2014). "Here, we found that cardiomyocyte-specific deletion of mouse AARS2 exhibited evident cardiomyopathy with impaired cardiac function, notable cardiac fibrosis, and cardiomyocyte apoptosis." (PMID 40371904, 2025). "The results collectively indicate that the deletion of Aars2 in cardiomyocytes results in abnormal cardiac function and fibrosis in mice, displaying characteristics of cardiomyopathy." (PMID 40371904, 2025). "The deletion in combination with the p.(Arg580Trp) (located in the β-barrel domain and impacting the stability of the AARS2 protein) resulted in cardiomyopathy." (PMID 33924034, 2021). "We identified mutations in the gene for mitochondrial alanyl-tRNA synthetase (AARS2) in a phenotype that differs from the other reported mtARS defects, being clinically a fatal early onset cardiomyopathy." (PMID 25705216, 2015). "This study showed that AARS2 plays a crucial role in salvaging cardiomyocytes from ischemic stress via fine-tuning PKM2-mediated energy metabolism, thus presenting novel therapeutic targets and potential small molecules for treating cardiomyopathy and MI." (PMID 40371904, 2025). "Therefore, future investigations are needed to address how AARS2 regulates mitochondrial function in cardiomyocytes, how AARS2 interacts with PKM2 complex to regulate mitochondrial metabolism, and how the AARS2-PKM2 signaling is related to the pathogenesis of human cardiomyopathy." (PMID 40371904, 2025).
ovarian failure (11 papers, 2017 to 2025). "Yet, recessive ALSP with ovarian failure linked to AARS2 (alanyl-transfer (t)RNA synthase 2) mutations (LKENP) is a mitochondrial disease and not a primary microglial leukoencephalopathy." (PMID 35683020, 2022). "Interestingly, although the male patients are absent from any endocrine diseases and hypogonadism, all of the females are diagnosed with ovarian failure, suggesting that analysis of the AARS2 gene should be prioritized when this sign is displayed in female patients." (PMID 31106991, 2019).
Ataxia (5 papers, 2014 to 2024). Ataxia refers to impaired coordination of voluntary muscle movement. "Different mutations in AARS2 were found to give rise to ataxia, spasticity and cognitive defects." (PMID 28516087, 2017). "Moreover, compound heterozygous mutations in AARS2 and DARS2 were detected in two male patients with slowly progressive ataxia and peripheral neuropathy." (PMID 37237429, 2023).
CADASIL (3 papers, 2017 to 2019). "Common genetic leukoencephalopathies discussed in detail include CSF1R, AARS2, cerebral arteriopathy with subcortical infarcts and leukoencephalopathy (CADASIL), and mitochondrial and metabolic disorders." (PMID 30467211, 2019).
lactic acidosis (3 papers, 2019 to 2021). Metabolic acidosis characterized by the accumulation of lactate in the body. "Moreover, AARS2 was found to be the disease gene for early-onset fatal hypertrophic cardiomyopathy with lactic acidosis." (PMID 34277617, 2021). "In contrast, we report two unrelated patients presenting with fatal infantile cardiomyopathy, lactic acidosis and respiratory failure, with severe multiple OXPHOS defects and who harboured biallelic AARS2 variants but not the recurrent founder allele." (PMID 30285085, 2019).
Adult onset (2 papers, 2019). Onset of disease manifestations in adulthood, defined here as at the age of 16 years or later. "Several cases of adult-onset leukodystrophy were recently shown to be caused by bi-allelic mutations in AARS2, the gene encoding the mitochondrial alanyl-tRNA synthetase, expanding the spectrum of adult onset neuroaxonal degeneration disorders." (PMID 31775912, 2019).
Brain atrophy (2 papers, 2021 to 2025). Partial or complete wasting (loss) of brain tissue that was once present. "However, the differences in radiological images between the two gene encoding mutations have been identified in the corpus collosum, in the regions with severe brain atrophy and in patients with AARS2 gene mutations lack the unique calcifications that are seen on the computed tomography (CT)." (PMID 40443872, 2025).